IL6 (interleukin 6)
Diseases named in the same sentence as IL6 in open-access papers (continued):
Sharing a sentence is not in itself a finding about the gene and the disease.
Cognitive impairment (continued). "Consistently, we also showed the potential link on the occurrence of cognitive impairment and the elevation of IL-6 and TNF-α in peripheral blood of preterm rats, which might be induced by the disrupted intestinal microflora." (PMID 36061856, 2022). "Our previous studies indicated that peripheral burns and traumatic surgical wound could induce the dysfunction of BBB and thus cognitive impairment through IL-6 and IL-1β." (PMID 36353359, 2022). "Therefore, trans-signaling is the mechanism whereby IL-6 produces postoperative cognitive impairment as suggested for this cytokine’s other neuropathologic effects." (PMID 36778590, 2022). "Using the AHBA, we also demonstrated that the MTG significantly overexpressed a highly interconnected number of genes in an interaction network with IL-6 together with a set of overexpressed genes for epilepsy, cognitive disorder, schizophrenia, psychotic disorder, and autism spectrum disorder." (PMID 35353173, 2022). "Furthermore, cognitive impairment caused significantly decreased levels of 5-HT, GABA, and BDNF, and increased levels of GR, CRH, IL-6, and TNF-α in rat blood." (PMID 36061856, 2022). "A recent study showed that Tau can activate microglia through the PQBP1-CGAS-STING pathway, and the activated microglia can produce IL-1β, TNF-α, IL-6 and other inflammatory factors through NF-κB transcription factor, ultimately leading to cognitive impairment in mice." (PMID 36466655, 2022). "We then applied MINO, recombinant IL-6 protein and IL-6 neutralizing antibody to manipulate microglia activities and found that microglia modulation in BLA was associated with changes in I/R-induced cognitive impairment, further supporting the BLA involvement." (PMID 36160165, 2022). "After long-term isoflurane anesthesia, the GJs formed by Cx43 in the mouse hippocampus and primary mouse astrocytes were significantly reduced, GJs function was impaired, hemichannel activity was enhanced, the levels of IL-1β and IL-6 were increased, and mice showed significant cognitive impairment." (PMID 35255943, 2022). "Dexmedetomidine could reduce the incidence of cognitive impairment after intestinal I/R injury, which may be related to decreased levels of inflammatory cytokines IL-1β, IL-6, C-reactive protein, and TNF-α." (PMID 35945306, 2022). "Napping has been related to higher levels of inflammatory markers, including IL-6 levels, which may induce cognitive impairment." (PMID 36109701, 2022). "Research indicates that the increased expression of IL-6 and the decline of Tregs may be related to the cognitive disorder of patients with vascular cognitive impairment (VCI)." (PMID 34912208, 2021). "We hypothesized that tau traffics from neurons to microglia via extracellular vesicles (EVs), leading to IL-6 generation and cognitive impairment." (PMID 33980987, 2021). "The exited tau or p-tau could travel with the assistance of EVs or non-EVs pathway, and enter microglia, activating the NF-kB signaling pathway and leading to IL-6 generation and cognitive impairment." (PMID 33980987, 2021). "In sevoflurane-induced cognitive impairment in adult rats, the addition of dexamethasone improved short-term and long-term cognitive impairment in adult rats and reduced the expression of the inflammatory cytokine IL-6." (PMID 34869762, 2021). "In addition, a study of rats showed that blood transfusions increase interleukin-6 levels and lead to neuroinflammation and subsequent cognitive impairment." (PMID 34006239, 2021). "Women with cognitive impairment had significantly higher IL-6 concentrations (4.1 (0.8) pg/mL vs. 2.5 (0.2) pg/mL, p = 0.004), and were less educated (12.7 (0.7) years vs. 14.1 (0.2) years, p = 0.03) and less physically active compared to cognitively normal women." (PMID 34371834, 2021). "Animal experiments also found that pain may aggravate cognitive impairment by changing the levels of inflammatory factors such as IL-6 and IL-1β in the plasma of rats." (PMID 33730999, 2021).
Cognitive impairment (continued). "LLD is a risk factor of dementia; thus, the outcomes merely prove that IL-6 is not a single or direct risk factor of cognitive impairment." (PMID 34299040, 2021). "We also used GW486936–39, an inhibitor of EVs generation, to assess whether inhibition of EVs generation can attenuate sevoflurane-induced tau trafficking and IL-6 generation in vitro, and cognitive impairment in mice." (PMID 33980987, 2021). "Furthermore, a 20 year cohort observed a correlation of cognitive impairment and higher or increasing levels of IL-6 over the years." (PMID 33918172, 2021). "IL-6 was the only marker found to be higher in participants with cognitive impairment, although the association did not meet the threshold for statistical significance." (PMID 36043690, 2021). "In young IL-6 knockout mice, sevoflurane increased Tau phosphorylation but did not cause mitochondrial dysfunction, synaptic loss or cognitive impairment." (PMID 34589883, 2020). "In our own work, increased expression of IL-6 was correlated with a resiliency to Alzheimer's pathology, defined as human subjects with no neuronal loss or cognitive impairment even in the presence of plaques and tangles associated with Alzheimer's." (PMID 31871276, 2020). "Together, these data demonstrated the interactions of Tau phosphorylation, IL-6 elevation and mitochondrial dysfunction and such interactions could lead to reduction in synapse number and cognitive impairment in young mice." (PMID 34589883, 2020). "Consistently, we showed that idebenone mitigated the sevoflurane-induced mitochondrial dysfunction, synaptic loss, and cognitive impairment, without altering Tau phosphorylation and IL-6 elevation, in the present studies." (PMID 34589883, 2020). "Here we showed that sevoflurane increased Tau phosphorylation and caused IL-6 elevation, mitochondrial dysfunction, synaptic loss and cognitive impairment in young wild-type, but not Tau knockout, mice." (PMID 34589883, 2020). "Furthermore, elevated IL-6 level constitutes a significant predictor of transition from mild cognitive impairment to Alzheimer’s disease and progression of this disease in older individuals." (PMID 31129771, 2019). "Nevertheless, there are some studies on the peripheral IL-6 that may be a useful biological marker to correlate with the severity of cognitive impairment." (PMID 31277647, 2019). "The increased levels of IL-6, TNF-α are associated with increased Aβ production, decreased Aβ clearance, tau hyper phosphorylation, synaptic dysfunction, and cognitive deficits." (PMID 31680874, 2019). "The increase of TNF-α and IL-6 expression might trigger the disruption of BBB in the brain, which eventually caused cognitive impairment in the 8-week STZ rats." (PMID 29867440, 2018). "Previous studies also showed that HHcy may result in neuroinflammation as indicated by elevated levels of IL1β, TNFα and IL6 in mice brain tissue, and these inflammatory mediators were all shown to independently result in cognitive impairments." (PMID 30425189, 2018). "The future studies should assess whether the BBB disruption and cognitive impairment are alleviated by blocking the TNF-α or IL-6 signaling." (PMID 29867440, 2018). "The specific mechanism that links hsCRP, IL-6, and cognitive deficit is not fully understood." (PMID 28951620, 2017). "Our hypothesis is that the anesthesia/surgery induces an age-associated and IL-6 dependent increase in BBB permeability, leading to cognitive impairment in mice." (PMID 28848542, 2017). "Our results suggest that elevated IL-6 levels may play the role in cognitive impairment and serve as potential inflammatory biomarker of deterioration in schizophrenia." (PMID 25214388, 2015). "Nevertheless, our results indicate that elevated IL-6 level may play additional role in the development of cognitive deficits described in schizophrenia and may further contribute to deterioration observed in the course of the disorder." (PMID 25214388, 2015).
Cognitive impairment (continued). "In an evaluation of IL-6 deficient animals, injection of lipopolysaccharide (LPS, shown to inhibit memory and learning in animals) failed to induce cognitive impairments suggesting IL-6 plays a key role in interrupting the process of memory and learning." (PMID 26538823, 2015). "In turn, cognitive impairments observed in schizophrenia might be the consequence of subclinical inflammation manifested in elevated hsCRP and IL-6 serum levels." (PMID 25214388, 2015). "The relationship between the therapy and the cognitive impairment could be partially mediated by elevation of plasma IL-6 levels." (PMID 24756915, 2014). "The relationship between inflammation and cognitive deficit was studied in a healthy young population after infusion of IL-6 to simulate the physiological acute-phase response, and the results indicated an explicit decrease in self-reported concentration and cognitive abilities." (PMID 24236147, 2013). "During the past few years, an increasing amount of evidence has supported the view that the excessive release of proinflammatory cytokines, including tumor necrosis factor (TNF)-α, interleukin (IL)-1β and IL-6, is involved in cognitive impairment after surgery and anesthesia." (PMID 23613842, 2013). "Also, a recent study demonstrated an increased production of IL-6 and IL-10 in mild cognitive impairment suggesting that immune activation is an early phenomenon that precedes AD." (PMID 22428008, 2012). "Brain expression of IL-6 has been shown to mediate the sickness behavior, a syndrome of neurocognitive changes in response to acute infection which includes lethargy, confusion, and cognitive deficits." (PMID 19436757, 2009). "However, chronic or high increases in IL-6 levels in the brain lead to neuronal and cognitive impairments." (PMID 19284588, 2009). "Our results suggest that TNF-α, but not IL-6, is strongly linked to the risk of cognitive impairments in middle-aged women, indicating that TNF-α may be a critical marker of early neurodegenerative changes in this group." (PMID 40137151, 2025). "Additionally, our observation of poor handgrip strength (a core frailty marker) in SCD-SG and MCI-SG subgroups reinforces prior links between IL-6, reduced muscle mass, and cognitive impairment, but contextualizes this within preclinical AD—where intervention potential is greatest." (PMID 41383333, 2025). "Moreover, cognitive disorder scores were positively related to IL-6 levels." (PMID 38877455, 2024). "From a biomarkers experimental point of view, these results have been confirmed in structural neuroimaging studies since increased IL-6 serum levels were associated with global brain atrophy and white matter lesions at the Magnetic Resonance Imaging in people without cognitive impairment." (PMID 36915478, 2023). "IL‐6 elevation in the hippocampus may stimulate the release of excitatory neurotransmitters, alter the balance of excitatory and inhibitory processes and, by doing so, may further contribute to cognitive impairment." (PMID 36811295, 2023). "Our analysis revealed that, in patients with cognitive impairment due to AD, (i) sPECAM-1, sP-, sE-Selectins, and IL6 were associated with amyloid and tau pathology; (ii) sP-Selectin, sNCAM, and the decrease of IL10 with neurodegeneration; and (iii) LPS and IL1β with cognitive impairment." (PMID 37254223, 2023). "Of importance, elevated levels of interleukin-6 (IL-6), C-reactive protein, and chitinase 3-like protein in cerebrospinal fluid of aged patients are positively correlated with their cognitive disorders, suggesting that chronic neuroinflammation takes part in cognitive impairment." (PMID 36932450, 2023). "Additionally, the disturbance of the intestinal microbial flora has the potential to initiate the secretion of peripheral pro-inflammatory cytokines, namely IL-1β and IL-6, resulting in heightened permeability of the blood-brain barrier, disruption of the CNS, and subsequent cognitive impairment." (PMID 38108273, 2023).
Cognitive impairment (continued). "Thus, we hypothesized that the anti-inflammatory effects of A. muciniphila involved downregulation of IL-6, thereby impeding further cognitive impairment in aged mice." (PMID 37254162, 2023). "Furthermore, we found that the cognitive disorder and altered intestinal microflora structure in preterm rats were associated with decreased levels of 5-HT, GABA, and BDNF, and increased levels of GR, CRH, IL-6, and TNF-α in serum." (PMID 36061856, 2022). "Thus, tau trafficking could occur from neurons to microglia to generate IL-6, leading to cognitive impairment." (PMID 33980987, 2021). "Additionally, PARK6-associated PD patients have also shown PINK1 deficiency and its impact on increased generation of pro-inflammatory cytokines and chemokines (e.g., IFNβ1, IL-6, IL-12, IL-13, CCL2, CCL4, and CXCL1), loss of NCs, and the development of cognitive defects." (PMID 34239490, 2021). "Importantly IL-6, IL-1β and IFNβ or IFN-dependent responses were exaggerated in older animals, both in plasma and in brain and this was associated with significantly worse cognitive impairments in aged animals." (PMID 33442686, 2021). "Moreover, sevoflurane increased Tau phosphorylation and IL-6, but did not cause mitochondrial dysfunction, synaptic loss and cognitive impairment in CypD KO mice." (PMID 34589883, 2020). "However, genetic polymorphism of TNF and IL-6 cytokines did not play a significant role to the cytokine fluctuations as well as cognitive impairment in Asian cohort." (PMID 32102503, 2020). "Taken together, these data, obtained from both Tau KO and IL-6 KO mice, indicated that IL-6 elevation in hippocampi of young mice was dependent on Tau, but independent of mitochondrial dysfunction, synaptic loss and cognitive impairment in young mice." (PMID 34589883, 2020). "Moreover, idebenone mitigated the sevoflurane-induced mitochondrial dysfunction, synaptic loss, and cognitive impairment, but not the sevoflurane-induced increase in Tau phosphorylation and IL-6 elevation." (PMID 34589883, 2020). "Finally, sevoflurane increased Tau phosphorylation and IL-6 amount, but did not induce synaptic loss and cognitive impairment, in young CypD knockout mice or WT mice pretreated with idebenone, an analog of co-enzyme Q10." (PMID 34589883, 2020). "In addition, increased miR-26b-5p expression could inhibit the activation of microglia and the production of interleukin-6 in hypoxia-ischemia, thus alleviating the cognitive impairment." (PMID 30901579, 2019). "Moreover, increased miR-26b expression in the hippocampal CA1 area in the VCI rat model could inhibit the activation of microglia and the production of IL-6 as well as reduce neuronal apoptosis, thus alleviating the cognitive impairment." (PMID 29937716, 2018). "Even though the current study did observe an association between plasma IL-6 levels and self-perceived cognitive impairment, we did not observe a dose response change of plasma IL-6 levels for each addition of the minor allele due to the dominance of the GG genotype (98.8%) in the local population." (PMID 27701469, 2016). "Henceforth, the absence of association between the IL6-174 G/C polymorphism and cognitive impairment could be attributed largely to the monomorphic nature of the SNP in the local population." (PMID 27701469, 2016). "An association between increased levels of IL-6 and worse cognitive performance has been shown in patients with Parkinson’s disease (PD) and dementia (a condition resembling DLB in regard to neuropathological changes and symptoms) and patients with PD with cognitive impairment." (PMID 26434635, 2015). "These evidences suggested that IL-6 might be a more appropriate marker for cognition impairment, such as the MHE in the current study Although literature has shown an increased serum level of TNF-α in cirrhotic patients with HE, we did not detect such a phenomenon in the current study." (PMID 26039496, 2015).
Cognitive impairment (continued). "Therefore, the elevation of circulating IL-6 levels may be one of the factors important in cognitive impairment in cancer patients treated with radiotherapy." (PMID 24756915, 2014). "Pilot data from a small sample of patients with FEP and healthy controls show a relationship between increased inflammation parameters (IL-8 and IL-6) and cognitive impairments across both groups, indicating that immune markers may be related to cognitive function in psychosis." (PMID 24409157, 2014). "Increased pro-inflammatory cytokines levels (TNFα, Interleukin-6, Interleukin-1β), combined with decreased levels of anti-inflammatory cytokines (Interleukin-10), have been correlated with cognitive deficits suggesting that early inflammatory changes may be detrimental." (PMID 22838967, 2012). "IL-6, TNF-α, and IL-1β levels during chronic neuroinflammation or cognitive impairment represent chronic neuroinflammation or cognitive impairment." (PMID 41516374, 2026). "The areas under the ROC curve (AUC) for IL-6, TNF-α, and NSE in assessing cognitive impairment were 0.842, 0.833, and 0.855, respectively." (PMID 41624546, 2026). "Beyond well studied CRP, IL-6 and TNF-α, literature on other chemokines is sparser and mainly focus on clinically defined AD or mild cognitive impairment (MCI)." (PMID 39824904, 2025). "Regarding neuroinflammation, STZ model group showed raised NF-κB, IL-6, and BACE-1 to add explanation of cognitive impairment occurred in this study." (PMID 40381124, 2025). "Pro-inflammatory cytokines such as interleukin-6 (IL-6) activate kynurenine pathway enzymes, increasing KYNA synthesis and worsening cognitive deficits, particularly in patients with elevated cytokine levels." (PMID 40137141, 2025). "Recent preclinical studies demonstrate that IL-6 trans-signaling in hippocampal CA1 neurons is both necessary and sufficient to induce postoperative cognitive impairment." (PMID 40951922, 2025). "This study demonstrates that prenatal valproic acid (VPA) exposure induces gut microbiota dysbiosis (Bacteroidia↓), exacerbating neuroinflammation (↑IL-1β/IL-6/TNF-α) and cognitive deficits in offspring via the microbiota-gut-brain axis." (PMID 40881681, 2025). "Elevated C-reactive protein (CRP), interleukin-6 (IL-6), and tumor necrosis factor-α (TNF-α) identify clinically relevant subgroups of patients characterized by greater severity, cognitive impairment, and poor treatment response." (PMID 41090786, 2025). "The Th17/Treg ratio imbalance exacerbates cognitive impairment by modulating STAT3 activation in mice, potentially illustrating the immune regulatory effects of STAT3 through IL-6-mediated Th17/Treg levels." (PMID 40843259, 2025). "AYAC both during and post-chemotherapy had higher rates of self-perceived and objective cognitive impairment, lower plasma BDNF, and elevated IL-4, IL-6, IL-8, IL-10, and IFN-γ compared to NC during follow-up." (PMID 40597835, 2025). "In elderly patients with constipation, the relative abundance of Blautia reduced, while Blautia was positively correlated with mild cognitive impairment and negatively correlated with TNF-α, IL-6, and IL-1β, which was consistent with our results." (PMID 38398836, 2024). "The results indicated that FH had protective effect against cognitive deficits induced by D-galactose through raising the protein expression of SOD1 and decreased genetic expression of IL-6 and AGE." (PMID 39446794, 2024). "Moreover, IL-6 also stimulates the HPA axis and cortisol production, which may have negative effects on CNS repair and recovery after acute stress and trauma as evidenced by acute cortisol associations with cognitive impairment after severe TBI." (PMID 38840141, 2024). "Our findings showed that treatment with apigenin alleviates cognitive impairment by reducing TNF-α and IL-6 levels in VPA-treated rats." (PMID 39720795, 2024).